EGFR (epidermal growth factor receptor)
Diseases named in the same sentence as EGFR in open-access papers (continued):
Sharing a sentence is not in itself a finding about the gene and the disease.
lung adenocarcinoma (continued). "Accumulating evidence demonstrated that mutations of EGFR were identified in 15–30% of lung adenocarcinomas in Caucasians and 40–60% in East Asians, indicating that the frequency of activated mutations of EGFR depends on ethnicity." (PMID 32677962, 2020). "Lung adenocarcinoma comprises some specific subgroups defined by oncogenic driver mutations, including the epidermal growth factor receptor (EGFR)-mutation." (PMID 33138052, 2020). "In a study of lung adenocarcinoma patients with leptomeningeal metastasis and known EGFR mutations in the primary tumor, patient-specific EGFR mutations were detected in the CSF cfDNA of all 26 patients." (PMID 32133357, 2020). "The C-index of the radiomics nomogram for the prediction of OS in lung adenocarcinoma in patients with an EGFR mutation was 0.840 and 0.803 in the training and validation cohorts, respectively." (PMID 33262942, 2020). "EGFR mutations, primarily occurring in exons 18 to 21, are some of the most frequent mutations in patients with lung adenocarcinoma." (PMID 32633046, 2020). "Our study investigated the patterns of recurrence and risk factors for LRR in EGFR-mutant stage III-pN2 lung adenocarcinoma after complete resection." (PMID 32922551, 2020). "The present study was designed to evaluate the association between antioxidant gene polymorphisms (SOD rs5746136 and SOD rs4880; CAT rs769218; OGG1 rs1052133; and TXN2 rs4821494) and EGFR-mutated lung adenocarcinoma." (PMID 32937815, 2020). "Activating somatic mutations in the tyrosine kinase domain of EGFR gene are prevalent in lung adenocarcinoma, which are associated with the clinical response to EGFR-tyrosine kinase inhibitors (TKIs)." (PMID 33426073, 2020). "In treatment-naïve patients with advanced lung adenocarcinoma under first-line EGFR-TKIs, prior use of β-blocker was associated with a better outcome." (PMID 33194721, 2020). "We recovered the gold-standard EGFRT790M mutation for gefitinib resistance in EGFR mutant lung adenocarcinoma cell lines." (PMID 33205120, 2020). "The results of this study suggest that in treatment-naïve patients with advanced lung adenocarcinoma receiving first-line EGFR-TKIs, prior β-blocker use was associated with a longer TTD and OS." (PMID 33194721, 2020). "Using this framework, we show that the combination of osimertinib and the SOS1 inhibitor BAY-293 shows marked efficacy in 3D spheroid culture and should be pursued as a therapeutic option to treat EGFR-mutated lung adenocarcinoma." (PMID 32897190, 2020). "It is reported that 40–50% cases of lung adenocarcinoma harboring epidermal growth factor receptor (EGFR) mutation in Asian patients." (PMID 32000711, 2020). "The alteration of epidermal growth factor receptor (EGFR) is a prominent feature in the development of lung adenocarcinoma and its mutation is an available site for target therapy." (PMID 32365566, 2020). "Intriguingly, it has been seen that driver fusions in lung adenocarcinomas co-occur with SETD2 mutations (16% of cases) in contrast with lung adenocarcinomas with EGFR, KRAS, BRAF and MET mutations, where the frequency of SETD2 mutations is only 2%." (PMID 32516941, 2020). "Patients with stage IIIb or IV lung adenocarcinoma with mutated epidermal growth factor receptor were enrolled retrospectively between March 2010 and December 2017." (PMID 32702917, 2020). "Thirteen lung adenocarcinoma patients suffered EGFR gene mutations, and fifteen lung adenocarcinoma patients had ALK gene mutations." (PMID 32296026, 2020). "Patients with early-stage lung adenocarcinoma (n = 171) were selected, and of these patients, 24 had EGFR mutations." (PMID 32277151, 2020). "The prevalence of EGFR mutations is relatively high in the Taiwanese population with lung adenocarcinoma." (PMID 32781755, 2020).
lung adenocarcinoma (continued). "This observational study evaluated the treatment outcomes of clinical factors on the patients with lung adenocarcinoma with epidermal growth factor receptor mutations who received tyrosine kinase inhibitors as first-line treatment." (PMID 32702917, 2020). "Both KRAS and EGFR mutations are identified almost exclusively in lung adenocarcinomas, similarly to rearrangements involving ALK and ROS1, which were described in 2007." (PMID 32604993, 2020). "EGFR TKIs, gefitinib, erlotinib, and afatinib, and ALK inhibitors, crizotinib and ceritinib, have prolonged progression-free survival (PFS) rates in advanced lung adenocarcinoma patients with sensitive EGFR mutations and ALK rearrangement, respectively." (PMID 33306683, 2020). "Afatinib exhibits a beneficial effect in patients with lung adenocarcinoma and leptomeningeal metastases harboring the EGFR exon 18 p.G719A mutation." (PMID 33014823, 2020). "Targeting lung adenocarcinoma with EGFR mutations among Asians is important because they have a significantly higher prevalence of the EGFR mutation compared with the Caucasians." (PMID 33489886, 2020). "For example, inconsistent mutation status of KRAS have been discovered between the primary and metastatic sites of lung adenocarcinoma, while the status of EGFR mutation is relatively consistent on the contrary." (PMID 33537237, 2020). "Treatment with epidermal growth factor receptor (EGFR)-tyrosine kinase inhibitors is more effective for patients with EGFR-mutated lung adenocarcinoma and acceptable for EGFR-mutated NSCLC with brain metastases." (PMID 33170151, 2020). "LUX-lung 3 and LUX-lung 6 trials were randomized studies that compared afatinib with cisplatin plus pemetrexed or cisplatin plus gemcitabine as first-line treatment in patients affected by lung adenocarcinoma harboring EGFR mutations." (PMID 32397295, 2020). "In the Asian population, the ratio of EGFR mutations in lung adenocarcinoma was about 40%–60%, which including the common L858R, Exon 19 in-frame deletion and T790M." (PMID 32365566, 2020). "Overexpression and mutation of EGFR have been shown to be from normal to early stages of lung adenocarcinoma, the abolition of it is considered as a clinical therapeutic option in NSCLC." (PMID 33292235, 2020). "More prospective studies focusing on the combination of afatinib and bevacizumab for untreated advanced EGFR-mutated lung adenocarcinoma are warranted." (PMID 33113888, 2020). "For example, studies of lung adenocarcinoma have revealed that epidermal growth factor receptor (EGFR) gene mutations occur more frequently in Asian populations than in Caucasians." (PMID 32344833, 2020). "In conclusion, the appearance of CA9 SNP rs2071676 is negatively associated with the rate of EGFR L858R expression in the male population of lung adenocarcinoma." (PMID 32365566, 2020). "Fifteen percent of lung adenocarcinomas are driven by epidermal growth factor receptor (EGFR) mutations." (PMID 32125091, 2020). "- The first study to perform mutant proteomic analysis of clinical tissue specimens obtained from patients of lung adenocarcinoma with EGFR oncogenic driver mutations." (PMID 32983988, 2020). "The present report is the first to demonstrate the safety and efficacy of dual EGFR and ABL TKI treatment in a patient with concomitant EGFR-mutated lung adenocarcinoma and CML." (PMID 32257476, 2020). "The proportion of strong PD-L1 (TPS ≥ 50%) expression in our study was 24% and higher than that of a previous study (9.9% in EGFR-mutated lung adenocarcinoma)." (PMID 32092879, 2020). "To explore B7-H3 effects on lung adenocarcinoma cells with EGFR mutation, we utilized CRISPR/Cas9 technology to delete B7-H3 gene in H3255 and HCC827 cell lines." (PMID 33426073, 2020). "The hierarchical clustering of patients according to protein abundance showed limited correlation with the proteome landscape and the EGFR mutation type in lung adenocarcinoma." (PMID 32616892, 2020).
lung adenocarcinoma (continued). "A cohort of 109 (77/32 in training/validation cohort) consecutive lung adenocarcinoma patients with an EGFR mutation was enrolled in this study." (PMID 33262942, 2020). "The association between CT features and EGFR mutation or ALK positivity in single primary lung adenocarcinoma (SPLA) has been well established and indicates a certain correlation between imaging and gene expression in SPLA." (PMID 32690092, 2020). "The data suggested that men carrying at least one A allele in CD44 rs11821102 had a higher risk of developing lung adenocarcinoma harboring the EGFR L858R mutation than those carrying homozygous GG alleles." (PMID 32344833, 2020). "In conclusion, the presence of EGFR mutations in advanced lung adenocarcinoma can predict a good prognosis; E19 dels prospect to have a better prognosis than other mutations, while an E21 mutation is expected to increase mortality." (PMID 32053675, 2020). "In this work, we have proposed one new way of constructing a deep leaning model using CT radiomics feature mapping to precisely recognize EGFR mutation of lung adenocarcinoma." (PMID 33643902, 2020). "Patients with lung adenocarcinoma harboring the EGFR S768I and G724S mutations appear less sensitive to first‐generation tyrosine kinase inhibitors than patients with sensitive EGFR.However, the patient benefited from treatment with afatinib." (PMID 32776462, 2020). "The present results suggest that CD44 rs11821102 G/A polymorphism is a potential candidate target for the prediction of lung adenocarcinoma with the EGFR L858R mutation in male patients." (PMID 32344833, 2020). "We report a case of an 80-year-old Japanese woman with lung adenocarcinoma harboring an EGFR-sensitizing mutation who was treated with osimertinib as the first-line treatment." (PMID 32796633, 2020). "The clinical efficacy of osimertinib for patients with lung adenocarcinoma harboring epidermal growth factor receptor (EGFR) exon 20 insertion mutations is unclear." (PMID 33080698, 2020). "On the other hand, the Exon 19 in-frame deletion is another common EGFR mutation that revealed a better disease-free survival and overall survival of lung adenocarcinoma compared to those with the L858R mutation." (PMID 32365566, 2020). "First, our study not only predicted survival outcomes in lung adenocarcinoma patients with EGFR mutations, but also identified patients with EGFR mutations who were likely to benefit from targeted therapy through rad score." (PMID 33262942, 2020). "When an uncommon EGFR mutation is detected in lung adenocarcinoma, TKI treatment should be actively considered." (PMID 32053675, 2020). "For example, EGFR tyrosine kinase inhibitors are effective for lung adenocarcinomas with EGFR mutations." (PMID 31474751, 2020). "Lung adenocarcinoma with EGFR mutations (primarily exon 19 deletions and L858R substitution in exon 21) is sensitive to targeted therapy by TKIs, such as gefitinib and erlotinib, which offers significant survival benefit to patients." (PMID 32923394, 2020). "Alveolar macrophages (AMs) are critical in the development of lung adenocarcinoma driven by epidermal growth factor receptor (EGFR) mutations." (PMID 32125091, 2020). "Two previous retrospective studies explored the effect of TKI treatment on survival outcomes in patients with resected lung adenocarcinoma and EGFR mutations from the US." (PMID 32660443, 2020). "Immunohistochemical stains were not performed for case 3 taken from the right upper lobe and harboring an EGFR exon 19 deletion mutation, supporting a diagnosis of lung adenocarcinoma." (PMID 32333643, 2020). "We revealed that these patients with the CD44 rs11821102-variant genotypes (GA + AA) exhibited a higher risk of lung adenocarcinoma with the development of the EGFR L858R mutation." (PMID 32344833, 2020).
lung adenocarcinoma (continued). "18F-FDG PET has shown some value in EGFR-mutated lung adenocarcinoma, and several studies have shown that image features extracted from 18F-FDG PET are associated with EGFR mutation status." (PMID 33370365, 2020). "Lung adenocarcinomas caused by (L858R) somatic mutation in the epidermal growth factor receptor (EGFR) show good therapeutic response to tyrosine kinase inhibitors." (PMID 33096790, 2020). "It was found that there were roughly the same EGFR mutations between lung adenocarcinoma tissues and CSF of nine patients, except for N1088, in which the EGFR mutation was undetectable in the CSF sample." (PMID 32711494, 2020). "We specifically address a translational potential of combined blockade of B7-H3-induced signaling and EGFR signaling in lung adenocarcinoma with EGFR Del E746-A750 mutation." (PMID 33426073, 2020). "Here, we first report a case of primary lung adenocarcinoma with EGFR gene mutation (del19) with metastasis to the uterine cervix." (PMID 33080701, 2020). "In Brazilian patients, mutational frequency of driver genes was reported in a large number of lung adenocarcinoma cases (n = 444), with EGFR mutated in 22.7% and K-RAS in 20.4% of the cases." (PMID 32971741, 2020). "Prevalence of epidermal growth factor receptor (EGFR) mutations in lung adenocarcinoma is about 15% in Caucasian patients." (PMID 32998450, 2020). "Patients with advanced lung adenocarcinoma harboring epidermal growth factor receptor (EGFR)-activating mutations showed a significant progression-free survival (PFS) benefit with reduced side effects by treatment with tyrosine kinase inhibitor (TKIs)." (PMID 32082997, 2020). "Clinical cases characterized by the presence of podoplanin-expressing CAFs display a poor response to EGFR tyrosine kinase inhibitors (EGFR-TKIs) in patients with lung adenocarcinoma harboring constitutively active mutations of EGFR." (PMID 32546182, 2020). "One lung adenocarcinoma patient acquired an EGFR p.T790M mutation, which was found 2 months before the imaging confirmed PD." (PMID 32738923, 2020). "EGFR mutations occur in approximately 10–35% of lung adenocarcinomas, with a higher prevalence of about 40–55% in East Asian patients." (PMID 33363040, 2020). "Inhibition of EGFR signaling by EGFR tyrosine kinase inhibitor (TKI) has been an effective targeted therapy for advanced lung adenocarcinomas with EGFR-activating mutations in tumor cells." (PMID 32957649, 2020). "Here, we investigate SOS1 and SOS2 as potential therapeutic targets in EGFR-mutated lung adenocarcinoma cells." (PMID 32897190, 2020). "Up to 30% of patients with lung adenocarcinoma in the Asian population have been shown to harbor epidermal growth factor receptor (EGFR) mutations." (PMID 32781755, 2020). "Previous studies reported that the mutation rate of EGFR in lepidic predominant lung adenocarcinoma was higher than that in adenocarcinoma of other subtypes." (PMID 32690092, 2020). "The preferential APOBEC (apolipoprotein B mRNA editing enzyme catalytic polypeptide-like)-induced hypermutation was observed in transformed SCLCs, whereas EGFR T790M-positive lung adenocarcinoma had rare APOBEC-associated mutations." (PMID 32762742, 2020). "For example, EGFR primary and secondary mutations (L858R and T790M, respectively) in the H1975 lung adenocarcinoma cell line were phased by both physical and synthetic long-read sequencing." (PMID 31474751, 2020). "Younger age, initial diagnosis of metastatic disease, and metastasis to the brain or different lobes were associated with LMC in patients with EGFR‐mutant lung adenocarcinoma." (PMID 31910497, 2020). "We report here a case of multiple intraventricular metastases from lung adenocarcinoma with EGFR G719X mutation." (PMID 32393286, 2020). "In our study, we observed that former β-blocker use prolonged survival in patients with lung adenocarcinoma harboring sensitive EGFR mutation receiving first-line EGFR-TKIs." (PMID 33194721, 2020).
lung adenocarcinoma (continued). "The efficacy of afatinib in combination with bevacizumab in untreated advanced epidermal growth factor receptor (EGFR)-mutated lung adenocarcinoma is currently unclear." (PMID 33113888, 2020). "L858R-associated lung adenocarcinomas are commonly responsive to treatment with the first-generation EGFR-TKIs erlotinib and gefitinib although they inevitably become unresponsive to the therapy after a progression-free period of 6 to 24 months." (PMID 33096790, 2020). "So we chose DNA as an objective genetic indicator to evaluate the biological behavior of lung adenocarcinoma in different EGFR mutation status." (PMID 32127953, 2020). "We investigated the predictive role of 18F-FDG PET/CT and clinicopathological features for EGFR mutations in lung adenocarcinoma with bone metastasis." (PMID 32742498, 2020). "Lysophosphatidylcholine acyltransferase 1 can up-regulate the PI3K/AKT pathway and promote EGFR mutation lung adenocarcinoma cell proliferation, invasion, and brain metastasis." (PMID 33537237, 2020). "Epidermal growth factor receptor (EGFR) mutations are one of the key characteristics of lung adenocarcinomas and their presence predicts treatment decision." (PMID 32570918, 2020). "We performed the retrospective study to investigate the risk factors of LRR in EGFR-mutant stage III-pN2 lung adenocarcinoma after complete surgical resection." (PMID 32922551, 2020). "We describe here the case of a patient with lung adenocarcinoma and leptomeningeal metastasis harboring an EGFR complex mutation (exon19del+K754E)." (PMID 33120820, 2020). "Here we demonstrated that male individuals carrying at least one A allele in CD44 rs11821102 had a higher risk of lung adenocarcinoma harboring the EGFR L858R mutation than those carrying homozygous GG alleles." (PMID 32344833, 2020). "Now, we are screening some lung adenocarcinoma cell lines harboring gene mutations, such as EGFR mutations, ALK rearrangement, KRAS mutations, and BRAF mutation, and other cell lines without gene mutations to detect MTAP gene and protein expression." (PMID 31965001, 2020). "This was a prospective single blind analysis of 35 skin biopsies from 31 patients with confirmed advanced EGFR‐mutated lung adenocarcinoma." (PMID 33015988, 2020). "A further in-depth network-based investigation on the tumorigenesis of lung adenocarcinoma under different EGFR mutations will provide clinically important information on proteogenomic landscapes in lung adenocarcinoma." (PMID 32616892, 2020). "Our findings give a clue that B7-H3-induced signaling is different in lung adenocarcinoma cells harboring EGFR L858R and Del E746-A750 mutations." (PMID 33426073, 2020). "Several oncogenic drivers have been identified in lung adenocarcinoma, including mutations in the epidermal growth factor receptor (EGFR), fusions of anaplastic lymphoma kinase (ALK), and rearrangements of ROS proto-oncogene 1 receptor tyrosine kinase (ROS1)." (PMID 32677962, 2020). "More importantly, dioscin overcomes tyrosine kinase inhibitor resistance by down-regulating phosphatase SH2 domain-containing phosphatase-2 (SHP2) expression in EGFR-mutated lung adenocarcinoma cells." (PMID 33061803, 2020). "Response to monotherapy with EGFR-TKIs is dependent on the presence of activating EGFR mutations, such as exon 19 deletions or L858R mutations, present in 16.6% of lung adenocarcinoma patients." (PMID 32234966, 2020). "When based on patients, EGFR mutations in the MPLA group were more common in women without a smoking history than in the wild-type EGFR group, similar to the clinical characteristics of patients with EGFR mutations in single primary lung adenocarcinoma (SPLA)." (PMID 32690092, 2020). "Our study reports a retrospective analysis on OS rates observed in patients with lung adenocarcinoma harboring somatic mutations either in EGFR and KRAS genes, or in less frequently studied genes, such as BRAF, PIK3CA, NRAS, and HER2 (niche mutations)." (PMID 32082488, 2020).